CPN1 (carboxypeptidase N subunit 1)
Description:
Protects the body from potent vasoactive and inflammatory peptides containing C-terminal Arg or Lys (such as kinins or anaphylatoxins) which are released into the circulation.
Synonyms: CPN; SCPN
Tractability: Small molecule: a high-quality ligand is known; it belongs to a druggable protein family. Antibody: its Gene Ontology location is reachable by antibodies, with high confidence; UniProt places it where antibodies can reach, with medium confidence; UniProt predicts a signal peptide or a membrane-spanning region. PROTAC: a small molecule that binds it is known.
Target class: Metallo protease; Metallo protease MC clan; Protease; Enzyme; Metallo protease M14B subfamily
Gene: Protein-coding gene on chromosome 10 (100,042,193 to 100,081,907, reverse strand). Ensembl gene ENSG00000120054.
Subcellular location: Secreted, extracellular space
Pathways (Reactome):
Immune System: Regulation of Complement cascade
Gene Ontology:
Molecular function: protein binding; metallocarboxypeptidase activity; carboxypeptidase activity; zinc ion binding
Biological process: peptide metabolic process; protein processing; bradykinin catabolic process; protein catabolic process; proteolysis; response to glucocorticoid
Cellular component: extracellular region
Genetic constraint (gnomAD): Loss-of-function variants: 35 observed, 45.93 expected, observed/expected ratio (o/e) 0.76, 90% interval 0.58 to 1.01. The upper end of that interval is the gene's LOEUF score, 1.01, which puts it in group 4 of 6, group 1 being the genes least tolerant of losing a copy. Missense variants: 561 observed, 629.96 expected, observed/expected ratio (o/e) 0.89, 90% interval 0.83 to 0.95. Synonymous variants: 224 observed, 248.14 expected, observed/expected ratio (o/e) 0.9, 90% interval 0.81 to 1.01.
Homologues: Orthologues: chimpanzee CPN1 (99% identical), macaque CPN1 (97% identical), rabbit CPN1 (87% identical), pig CPN1 (86% identical), dog CPN1 (86% identical), mouse Cpn1 (84% identical), guinea pig CPN1 (83% identical), rat Cpn1 (83% identical), tropical clawed frog cpn1 (68% identical), zebrafish cpn1 (65% identical). Paralogues in human: CPE (49% identical), CPD (46% identical), CPXM1 (45% identical), CPZ (45% identical), AEBP1 (43% identical), CPXM2 (42% identical), CPM (38% identical).
Diseases named in the same sentence as CPN1 in open-access papers:
CPN1 is named in the same sentence as 35 diseases in open-access papers, as found by Europe PMC text mining. Sharing a sentence is not in itself a finding about the gene and the disease. The quoted sentences say what the papers report.
breast carcinoma (8 papers, 2020 to 2023). "Consequently, CPN1 levels could be used as a potential prognostic biomarker for the stratification of breast cancer patients according to their risk." (PMID 34711246, 2021). "CPN1 was considered a tumor biomarker for assessing invasion and metastasis status in breast cancer patients." (PMID 37719007, 2023). "Previously, we have found that the overexpression of carboxypeptidase N1 (CPN1) facilitated metastasis in breast cancer cells." (PMID 35431930, 2022). "Data from a database showed that CPN1 is elevated in several specific types of breast cancer, compared with normal and other non-triple-negative breast cancers, triple-negative breast cancer has higher CPN1 mRNA expression." (PMID 34711246, 2021). "Furthermore, preliminary serologic experiments demonstrated that CPN1 is highly expressed in the serum of breast cancer patients, which is significantly related to metastasis of TNBC." (PMID 35431930, 2022). "Serology showed that CPN1 was expressed highly in both breast cancer and metastatic breast cancer and could be shown to be detected with a higher sensitivity and specificity than CA153." (PMID 34711246, 2021). "CPN1 was also reported to be useful in early detection of breast cancer." (PMID 32256857, 2020). "Also, the results from serological experiments indicated that the serum CPN1 may be a potential biomarker comparedwith CA15-3 for breast cancer." (PMID 35431930, 2022). "Furthermore, cytological experiments were conducted to validate that CPN1 may serve an important part in aggression and metastasis of breast cancer." (PMID 35431930, 2022). "Firstly, we found that RAI14 and CPN1 are interacting proteins and explored the expression characteristics of RAI14 in breast cancer tissues by employing The Cancer Genome Atlas database." (PMID 36880986, 2023). "We examine the expression of CPN1 and RAI14 using the Western blot in different mammary carcinoma cell lines." (PMID 35431930, 2022).
COVID-19 (7 papers, 2021 to 2024). A disease caused by infection with severe acute respiratory syndrome coronavirus 2. "It is interesting to further explore the role of CPN1 in COVID-19 pathophysiology as this carboxypeptidase also inactivates the complement system." (PMID 35812405, 2022). "In patients with COVID-19, we observed an overexpression of plasma CPN1, which we suggest collaborates in BK1-8 accumulation." (PMID 35812405, 2022). "Our study provides additional evidence for a role of the kallikrein kinin-system in COVID-19; carboxypeptidase N (CPN1) was exclusively found in COVID-19 lung tissue, which would result in accelerated conversion of bradykinin to des-Arg9-bradykinin." (PMID 34000623, 2021). "Concomitantly, CPN1, the major BK degrading enzyme, was upregulated in patients with COVID-19." (PMID 35812405, 2022). "Additionally, it was recently reported that carboxypeptidase N subunit 1, which cleaves bradykinin into des-Arg9-BK, is overexpressed in COVID-19 patients." (PMID 36601349, 2022). "In addition, our results from HK Western blot suggest that BK1-8 levels in plasma of patients with COVID-19 could not only result because of the increased level of CPN1 but also by an increased e production of kinins, via increased degradation of HK." (PMID 35812405, 2022).
angioedema (5 papers, 2017 to 2025). Swelling involving the deep dermis, subcutaneous, or submucosal tissues, representing localized edema. "Recently and after the Symposium, families with recurrent angioedema combined with recurrent urticaria associated with mutations in either CPN1 or DAB2IP genes have been reported." (PMID 40053270, 2025). "The variants were transmitted as an autosomal-recessive trait, and combinations of CPN1 alleles cosegregated with angioedema clinical symptoms in patients." (PMID 38445235, 2024). "Our study results facilitated an understanding of molecular mechanisms underlying the association of cpn1 with HTN and angioedema." (PMID 28500283, 2017). "Thus, we hypothesized that prolonged cpn1 deficiency and cpn1 overexpression in animals can respectively cause HTN and angioedema and this hypothesis will be tested in future studies." (PMID 28500283, 2017). "Our results show that, in clinical practice, cpn1 can be a potential biomarker or therapeutic target for vascular diseases such as HTN, angioedema, and urticaria." (PMID 28500283, 2017). "The use of zebrafish as a model allows for the generation of transgenic or knockout animal models for studying cpn1-related HTN and angioedema." (PMID 28500283, 2017). "Thus, cpn1 might be used as a novel biomarker and therapeutic target for HTN and angioedema." (PMID 28500283, 2017).
triple-negative breast carcinoma (2 papers, 2021 to 2022). An invasive breast carcinoma which is negative for expression of estrogen receptor (ER), progesterone receptor (PR), and human epidermal growth factor receptor 2 (HER2). "In addition, the concentration of CPN1 fluctuated in patients with triple-negative breast cancer (TNBC) and in patients treated extensively with chemotherapy compared to CA153." (PMID 34711246, 2021). "CPN1 and RAI14 were expressed in triple-negative breast cancer cell lines and were positively correlated." (PMID 35431930, 2022).
coronary artery disease (1 paper, 2024). "Significantly elevated levels of CPN1 could be detected in coronary artery disease patients, and the ROC analysis of CPN1 showed that this parameter can also distinguish the two diagnostic groups." (PMID 39767589, 2024).
Diabetes (1 paper, 2022). "B1R antagonism and pharmacological blockade of CPN1 exerted similar beneficial effects in a rat model of Diabetes." (PMID 39086962, 2022). "ACE2 deficiency has been directly linked to defects in Insulin secretion and interestingly, B1R as well as CPN1, the enzyme that converts BK into the B1R ligand DABK have been researched as preclinical targets in the context of Diabetes." (PMID 39086962, 2022).
heart failure (1 paper, 2022). Inability of the heart to pump blood at an adequate rate to meet tissue metabolic requirements. "Conventional treatment for heart failure could attenuate the changes in up- (CPN1, and C3) and down-regulated proteins (serum albumin precursor, albumin isoform X1, IGLC, and fetuin-B) in stage C CHF." (PMID 35203200, 2022).
Hepatic steatosis (1 paper, 2013). Steatosis is a term used to denote lipid accumulation within hepatocytes. "This final list includes six genes associated with ALT elevation and/or hepatic steatosis (MAPK10, CPN1, TRIB1, PNPLA3, SAMM50 and MICAL3)." (PMID 23813869, 2013).
Hypertension (1 paper, 2017). The presence of chronic increased pressure in the systemic arterial system. "Thus, the relationship among Cpn1, bradykinin, and hypertension (HTN) should be investigated in the future, and Cpn1 can potentially serve as a biomarker for HTN." (PMID 28500283, 2017).
ischemia (1 paper, 2022). A hypoperfusion of the BLOOD through an organ or tissue caused by a PATHOLOGIC CONSTRICTION or obstruction of its BLOOD VESSELS, or an absence of BLOOD CIRCULATION. "In the present study, we show that cardiomyocyte specific CPNS1 deletion decreases cardiac injury following ischemia–reperfusion, supporting that activation of CPN1/2 contributes to cardiac injury during ischemia–reperfusion." (PMID 34997008, 2022).
lymph node metastasis (1 paper, 2021). "Analysis of the data revealed that CPN1 over-expression could be consistently linked to adverse clinicopathological features such as lymph node metastasis and the pathological stage (pTNM) (P < 0.05)." (PMID 34711246, 2021). "The data analysis revealed that CPN1 expression was positively correlated with TNM stage (P = 0.019) and lymph node metastasis (P = 0.006)." (PMID 34711246, 2021).
Salmonella Infections (1 paper, 2024). Infections with bacteria of the genus SALMONELLA. "We found that IL-1β-/- mice express 4-fold higher transcription levels of Cpn1 after Salmonella infection, compared with WT mice." (PMID 38236896, 2024).
tumor (5 papers, 2015 to 2023). "The associated trajectories of serum CPN1 measurements and radiographic tumor burdens for these two typical patients are shown." (PMID 34711246, 2021). "Follow-up ultrasound revealed a reduction of tumor burden and downsizing of lymph nodes, which was corresponded to the trend of decreasing serum CPN1 levels." (PMID 34711246, 2021). "Patient 025 had a greater decline in CPN1 levels and tumor diameter (decline rate: 76.9%and 21.7%, respectively) than patient 028(decline rate: 48.2%and 18.8%, respectively)." (PMID 34711246, 2021). "Longitudinal comparison of both patients revealed a better decrease rate of CPN1 than that of the tumor diameter, which may be more valuable for treatment efficacy determination." (PMID 34711246, 2021). "In addition, CPN1 production in serum is correlated with tumor size, clinical stage, and metastasis, which indicated that CPN be used as an innovative tumor marker for ancillary diagnosis of IBC metastasis." (PMID 34711246, 2021).
infection (3 papers, 2014 to 2024). The state of being infected such as from the introduction of a foreign agent such as serum, vaccine, antigenic substance or organism. "However, infected IL-1β-/- mice treated with CPN1 inhibitor suffered from over 60% mortality, while vehicle-treated IL-1β-/- mice were completely resistant to infection-induced mortality." (PMID 38236896, 2024).
cardiac diseases (1 paper, 2022). "The attenuation of ER stress or the prevention of CPN1 activation is a potential strategy to protect complex I in cardiac diseases that manifest increased ER stress as a consequence of impaired protein folding and processing." (PMID 36013387, 2022).
CPN1 also shares sentences with these, for which no sentence is quoted: cancer (3 papers); urticaria (2); age-related macular degeneration (1); asthma (1); Brain atrophy (1); breast tumors (1); Cirrhosis (1); colitis (1); inflammation (1); Insulin resistance (1); mood disorder (1); myocardial infarction (1); myopathy (1); pertussis (1); respiratory diseases (1); respiratory infections (1); staphylococcus aureus infection (1); Stroke (1); systemic lupus erythematosus (1); viral infections (1).